IL6 (interleukin 6)
Diseases named in the same sentence as IL6 in open-access papers (continued):
Sharing a sentence is not in itself a finding about the gene and the disease.
COVID-19 (continued). "Elevated plasma Gal-9 levels in COVID-19 patients, for instance, correlate with increased TNF-α and IL-6 expression in monocytes stimulated with rGal-9." (PMID 39951917, 2025). "Our study reveals persistent inflammation following COVID-19 with serum trajectories of novel markers (HBP and SAA), demonstrating dynamics similar to traditional markers (CRP and IL-6)." (PMID 40621180, 2025). "In the case of COVID-19, SARS-CoV-2 infection triggers a cascade of molecular disturbances, including excessive cytokine release (IL-6, TNF-α, and IL-1β), microglial activation, and oxidative stress, leading to neuroinflammation and neuronal dysfunction." (PMID 40126810, 2025). "Among patients with COVID-19 receiving Empagliflozin, a significant correlation was observed between IL-1, TNF-alpha, IL-6, and blood glucose levels." (PMID 40134446, 2025). "Moreover, the anti-inflammatory properties of Febuxostat, through inhibition of the JAK/STAT and NF-κB pathways and subsequent reduction in pro-inflammatory cytokines such as IL-1β, IL-6, and TNF-α, may underlie its protective effects against COVID-19-related hyperinflammation and organ damage." (PMID 41235116, 2025). "IL1B, IL6, and TNF are pro-inflammatory cytokines that contribute to the cytokine storm observed in severe COVID-19 cases, leading to acute respiratory distress and systemic inflammation." (PMID 41471341, 2025). "Outcomes immune/inflammatory markers: In COVID-19, lymphocytes are often reduced (indicating low immune response), while enhanced inflammatory markers such as C-reactive protein (CRP) and cytokine IL-6 are significant predictors of severe or Long COVID." (PMID 40910061, 2025). "Higher levels of IL-6, ESR, ferritin and CRP were observed in the population of patients with COVID-19 and diabetes." (PMID 40904859, 2025). "A similar dysregulated immune response, marked by low levels of type I and III IFNs alongside elevated chemokines and high IL-6 expression, contributes to the pathogenesis of SARS-CoV-2 infection and the development of COVID-19." (PMID 40692679, 2025). "We determined that inflammation (CRP, IL-6, fibrinogen, LDH, ferritin) and coagulation (D-dimer, PT) parameters and liver enzymes (AST, ALT, GGT) were preferentially increased in male COVID-19 patients." (PMID 40868247, 2025). "A study analyzing 109 COVID-19 patients found that LYM and IL-6 levels are closely related to the severity of the patients and are independent predictors of their mortality." (PMID 41450918, 2025). "Cytokine concentrations (IFN-γ, IL-1Ra, IL-4, IL-6, IL-9, IL-13, and TNF-α) were higher in the breast milk from the breastfeeding mothers with symptomatic and asymptomatic COVID-19 compared with the control group at both sampling times." (PMID 40141241, 2025). "As expected, plasma concentrations of several inflammatory mediators, including IL-1α, IL-6, IL-18, IP-10, HGF, MCP-3, and M-CSF, were elevated in patients with acute COVID-19, especially those with severe disease." (PMID 39847442, 2025). "People who died from COVID-19 and ARDS had higher levels of IL-6 in their blood compared to those who survived." (PMID 40895261, 2025). "Among patients with poor prognosis, IL-6, IL-17, and APTT levels were higher, and a larger proportion had a history of severe COVID-19 (36.8% vs 5.6%)." (PMID 41305706, 2025). "Elevated levels of proinflammatory cytokines, such as IL-6, IL-8, and TNF-α, have been identified, reflecting local inflammation and its possible connection to the systemic inflammatory state of COVID-19 patients." (PMID 39859366, 2025). "While sepsis can also trigger cytokine storms and immune dysregulation, COVID-19 exhibits a more stereotyped hyperinflammation pattern driven predominantly by SARS-CoV-2-specific mechanisms (e.g., IL-6/IL-1β dominance, endothelial injury)." (PMID 40936775, 2025).
COVID-19 (continued). "Critical COVID-19 cases showed higher levels of inflammatory markers (Bilirubin, D-dimer, PCR, and urea, as well as IL-8, IL-10, TNF-α, INF-α, IL-1β, IL-17A, IL-23, IL-6) than moderate and severe groups." (PMID 39861879, 2025). "IL-6 is a crucial cytokine in inflammation and the acute phase response; hence, the pattern seen here shows that the Ad26.COV2.S (Janssen COVID-19 Vaccine)indeed provokes a strong initial inflammatory response necessary for immune activation." (PMID 40406137, 2025). "Nees (AP) as a potential natural adjunctive therapy for COVID-19, with resulting trends indicating possible benefits in symptom improvement, fever and cough resolution, and reductions in CRP and IL-6 levels." (PMID 40822451, 2025). "This involves controlling gene activity, for instance, by phosphorylating the membrane-based Janus kinase (JAK) with IL-6, which activates the signal transduction and activation of transcriptional (STAT) in COVID-19." (PMID 40410684, 2025). "Our analysis revealed significantly higher serum levels of IL-6, CRP, SAA, and PCT in severe COVID-19 patients compared to mild cases, indicating a strong association with disease severity." (PMID 40046064, 2025). "Patients with severe COVID-19 who experience thromboembolic events often present with elevated inflammation markers, including CRP, IL-6, fibrinogen, and ferritin, suggesting a strong link to immunothrombosis." (PMID 40612950, 2025). "In pregnant women with acute COVID-19, a significant positive correlation between APTT, TT and a large subset of the tested inflammatory cytokines/chemokines was observed, including IL-6, INF-α2, MCP-1, IL-10, and IL-18." (PMID 40303405, 2025). "COVID-19–induced inflammation elevates key cytokines such as IFN-γ, IL-1β, and IL-6, which potently induce IDO1 expression in immune cells including macrophages, fibroblasts, and dendritic cells." (PMID 40949107, 2025). "The levels of pro-inflammatory cytokines IL-6 and TNF-α, which are key indicators of COVID-19 severity, were quantified in serum and lung tissue at 6/7 dpi." (PMID 40868984, 2025). "Persistent high levels of early response proinflammatory cytokines, including IL-6, TNF-α, and IL-1β, can trigger a cytokine storm in COVID-19 patients." (PMID 40571942, 2025). "Recent studies show COVID-19 convalescents had a higher level of CETP than the healthy cohort and lipoprotein lipase was impaired by the elevated IL-6 and TNF-α in addition to increased hepatic lipase in the LC cohort." (PMID 40335840, 2025). "Interleukin 6 (IL6) has been recognized to be the most important driver of immune dysregulation and ARDS in COVID-19 and a predictive factor for a severe form of the disease." (PMID 41141600, 2025). "Our results identify IL-6 and TNF as critical therapeutic targets against COVID-19 in SLE patients, whereas IL-10 relates closely to severe outcomes." (PMID 40643149, 2025). "Kynurenine was strongly correlated with IL-10, IL-8, IL-7, IL-6, IL-2R, IL-12, and IFN-α levels in patients with COVID-19." (PMID 41002992, 2025). "Notably, IL-2R, IL-6, IL-7, IL-8, and IL-10 showed lower correlations with the metabolites for the worst outcomes, indicating that these cytokines might have different regulatory mechanisms during severe COVID-19." (PMID 41002992, 2025). "When comparing the frequency of patients with elevated levels of IL-10, IL-6, and TNF-α and their combinations or overlaps, we found a significant difference (p < 0.001) between the non-, moderate, severe, and critical COVID-19 groups." (PMID 40508859, 2025). "Inflammatory cytokines and chemokines, including IL-1, IL-6, IL-8, IL-17, CCL-2, TNF-α, G-CSF, IP-10, MCP-1 and MIP, are elevated in COVID-19 patients." (PMID 40794529, 2025). "The analysis of cytokine profiles in pediatric patients with COVID-19, MIS-C, and healthy children revealed notable differences in levels of IL-1β, IL-6, IL-8, IL-12, TNF-α, and IFN-α levels." (PMID 40066463, 2025).
COVID-19 (continued). "In our study, COVID-19 recovering individuals with different degrees of microbial dysbiosis exhibited persistent inflammatory signaling of FGF2, MCP-1, IL-6, and IFN-γ." (PMID 38172612, 2024). "Other components, such as interleukins (IL-2, IL-6, IL-7, IL-10) and TNF-α are connected to severe COVID-19 symptoms, where cytokine storm (a sudden increase in cytokines) occurs instead of a healthy immune response (Fricke-Galindo and Falfán-Valencia 2021)." (PMID 38240884, 2024). "In the context of COVID-19, the cytokine storm involves key cytokines such as tumor necrosis factor-alpha (TNF-α), interleukin 6 (IL-6), and interleukin 1 (IL-1)." (PMID 39429337, 2024). "Because SARS-CoV-2 infection-induced cytokine storm plays a key role in the COVID-19 pathogenesis, we compared differences in CRP and IL-6 levels in serum derived from both CB and maternal blood." (PMID 39574146, 2024). "Elevated IL-6 levels contribute to severe lung damage, and both IL-6 and TNF-α play crucial roles in cytokine storm, ARDS, and mortality in COVID-19 patients." (PMID 38568894, 2024). "Using the residual nasopharyngeal swab samples, our study demonstrates the significant association between respiratory immune mediators (including IL-10, IL-6, MCP-1, and MCP-3) and COVID-19 severity." (PMID 39633683, 2024). "Our findings revealed that COVID-19 patients in the ICU had significantly higher levels of ferritin, hepcidin, zinc, CRP, and IL-6 compared with the other two study groups in both geographic regions." (PMID 39062181, 2024). "Furthermore, a Structure–Activity Relationship analysis revealed that furosemide’s sulfonamide groups may interact with cytokine sites such as tumor necrosis factor-alpha (TNF-α) and interleukin-6 (IL-6), potentially explaining its beneficial effects in COVID-19 management." (PMID 39065617, 2024). "We observed that the levels of the innate immune marker, sCD14, as well as cytokines IL-6, IL-8, and IFN-γ, were significantly lower in the long-COVID saliva than in the pre-COVID-19 saliva." (PMID 39597960, 2024). "The persistently high interleukin-6 (IL-6) and tumor necrosis factor-α (TNF-α) levels in severe COVID-19 patients are important products of toll-like receptor 4 (TLR4) signaling." (PMID 38165854, 2024). "A meta-analysis that included 13 studies in COVID-19 patients where MT was administered showed that there were significant reductions in TNF-α and IL-6 levels." (PMID 38674128, 2024). "Neutering IL-6 was shown to reduce cardiac fibroblast activation in mice, so we propose that tocilizumab may also have a bearing on combating myocardial fibrosis caused by COVID-19, but clinical epidemiological evidence is not currently available." (PMID 39444690, 2024). "This study underscores the importance of IL-6 and MCP as robust predictors of severe COVID-19, substantiating their role in clinical assessments to foresee patient deterioration." (PMID 39062105, 2024). "High granulocyte colony-stimulating factor (G-CSF) levels are detected in parallel with elevated serum levels of IL6 and IL10 in severe COVID-19." (PMID 38543303, 2024). "In a study on COVID-19 patients, a single injection of the monoclonal PCSK9 antibody evolocumab led to reduced serum IL-6 levels and improved outcomes compared to placebo at 30 days from baseline." (PMID 39051245, 2024). "Combinatorial blockade of IL-6 and TNF-α results in a significant increase of cardiomyocyte viability, indicating an opportunity for therapeutic intervention in severe COVID-19." (PMID 38041432, 2024). "We also observed a significant increased odds of severe COVID-19 (WHO Clinical Progression Scale score 6 to 10) for increased concentration of CRP, IL6, IP10, IL8, IL1RA, and suPAR." (PMID 39664394, 2024). "In patients with COVID-19, bio-ADM and IL-6 were significantly elevated in patients suffering from acute kidney injury during their in-hospital stay as well as reaching the combined endpoint." (PMID 38336628, 2024).
COVID-19 (continued). "An increased and uncontrolled production of cytokines such as interleukin-6 (IL-6), interleukin-1 (IL-1), and tumour necrosis factor-alpha (TNF) are reported in severe COVID-19 patients." (PMID 38863829, 2024). "The severe complications of COVID-19, notably ARDS, often involve a cytokine release syndrome characterized by elevated levels of IL-6, among other markers." (PMID 39065559, 2024). "Further, SLE and COVID-19 can interact via IFN-I/II and IFN-I/II receptors, promoting the levels of monokines, including interleukin (IL)-6/10, tumor necrosis factor-α, and IFN-γ, and elevating the incidence rate and risk of cytokine release syndrome." (PMID 38862942, 2024). "A comparative analysis of cytokines in BALF and blood plasma of severe patients with ARDS against the background of COVID-19 showed increases in the levels of TNF-α, IL-1α, IL-1β, IL-1ra, IL-6, IL-10, and IL-33 cytokines relative to healthy donors." (PMID 39457048, 2024). "Elevated levels of IL-6, IL-10, and TNF-α have been shown to predict clinical progression to severe forms of COVID-19." (PMID 39203987, 2024). "Given the well-established anti-inflammatory properties of curcuminoids, we further explored their role in modulating cytokines, including IL-6, IL-17, IFN-γ, and TNF-α, which are often elevated in COVID-19." (PMID 38730068, 2024). "Cytokines are messenger molecules of the immune system, including IL-6, IFN-α, IL-1β, IL-8, IL-10, IFN-γ, TNF-a, and C-reactive protein (CRP), and as such, they are closely related to the worst outcomes of COVID-19." (PMID 38012459, 2024). "The elevated serum levels of IL-6, IL-10, and TNF-α have been correlated with disease severity and mortality in COVID-19 patients." (PMID 38932387, 2024). "UIBC, TIBC, hepcidin/CRP, and hepcidin/IL-6 were lower, and IRF, ferritin/hepcidin, and hepcidin/iron were higher in severe and critical COVID-19 than in mild and moderate COVID-19." (PMID 38892911, 2024). "The ophthalmology department was able to confirm a left CRAO, and the lab tests confirmed the presence of inflammation (elevated IL-6) and elevated clotting (D-dimer), which pointed to CRAO occurring after the patient's COVID-19 diagnosis." (PMID 38576676, 2024). "Among the many cytokines with significantly greater cumulative exposure in COVID-19 were CXCL10, CCL8, CCL2, IL-6, and TNF-α (q < 0.05, Mann-Whitney)." (PMID 38502186, 2024). "High levels of IL-6, and consequently, C-reactive protein (CRP), are found in post-acute sequelae of COVID-19 (PASQ), also called long COVID or post-COVID-19 syndrome." (PMID 38248262, 2024). "The excessive production of pro-inflammatory cytokines, such as IL-6, TNF-α, and IL-1β, leads to a cytokine storm, which is a key driver of the severe manifestations of COVID-19." (PMID 39130641, 2024). "Only EPO, IL-6, and hepcidin/EPO differentiated patients with critical COVID-19 from those with severe disease course." (PMID 38892911, 2024). "Following the outbreak of the COVID-19 pandemic, IL-6, CRP, and D-dimer have been used as potential indicators to assess the intensity and prognosis of COVID-19 illness." (PMID 39759701, 2024). "The relationship between the expression of miR-9, the transcription factor NF-κB, and the pro-inflammatory cytokines IL-6, IL-1β, and TNF-α in a cohort of COVID-19 patients was investigated." (PMID 39201618, 2024). "IL-6, a pro-inflammatory cytokine that can be induced by IL-1β and a significant inducer of CRP, is consistently elevated in the serum of COVID-19 patients and strongly predicts poor prognosis." (PMID 39452786, 2024). "Of note, the Q-values were less significant for IL-6 or CRP (-log10 35.81 and 108.3, respectively, p<0.00001 for both), which are two common biomarkers of COVID-19 severity." (PMID 39835130, 2024). "This study confirms the significant predictive value of IL-6 and MCP for severe COVID-19, advocating for their inclusion in prognostic assessments of hospitalized patients." (PMID 39062105, 2024).
COVID-19 (continued). "Our study underscores the significance of monitoring Il-6 and WBC levels within 48 hours of ICU admission, potentially influencing COVID-19 patient outcomes." (PMID 38935767, 2024). "Early in the pandemic, Sinha and colleagues discovered two latent subtypes of COVID-19 ARDS, as defined by the Berlin criteria, using LCA of readily available clinical data and IL-6." (PMID 38383504, 2024). "Herein, we demonstrated the significant association between elevated levels of respiratory immune mediators (including IL-10, IL-6, MCP-1, and MCP-3) and COVID-19 severity." (PMID 39633683, 2024). "Despite evidence indicating elevated IL-6 and VWF in COVID-19, and some data supporting the use of IL-6 as a prognostic indicator, especially for oxygen requirement, neither IL-6 nor VWF were indicative of progression to severe disease in our cohort." (PMID 39459948, 2024). "The aim of this study was to analyze the potential relationship between the level of selected cytokines (IL-6, IL-10, IL-12, IL-15, TNF-α) and inflammatory markers (CRP, NLR, PLR, LMR, SII) and the duration of rehabilitation in patients after COVID-19." (PMID 39335569, 2024). "Further, it has been shown that the urine of COVID-19 patients contains increased levels of proinflammatory cytokines like IL-6, IL-8, and CXCL-10, and high urinary IFN-γ upon hospital admission proved to be a positive predictor of AKI in COVID-19 patients." (PMID 38398672, 2024). "Intraperitoneal administration of CML in zebrafish resulted in acute paralysis, impaired swimming ability, and a sharp increase in neutrophil infiltration, IL-6, and TNF-α levels, resembling the cytokine storm observed in COVID-19 patients." (PMID 39334708, 2024). "Several cytokines (GM-CSF and IL-6) and chemokines (MCP-1/CCL2, IL-8/CXCL8, and IP-10/CXCL10) were markedly increased in COVID-19 patients with a significant correlation with disease severity." (PMID 38855114, 2024). "Interleukin-6 (IL-6), as a mediator of the acute-phase inflammatory response in sepsis, ARDS, and COVID-19, is a key player in the ‘cytokine storm’ often observed and associated with ACB hyperpermeability." (PMID 39407979, 2024). "At the pandemic’s beginning, elevated cytokine levels (notably IL-6, GM-CSF, TNF, interferons, and IL-18) were commonly reported in severely ill patients with COVID-19, contributing to the cytokine storm." (PMID 39729489, 2024). "IL-10 is known to downregulate the inflammatory response, including the production of IL-6 and TNF-α, which are involved in the development of cytokine storms in severe COVID-19 cases." (PMID 39493183, 2024). "The seven pro-inflammatory cytokines (IL-6, IL-8, IL-15, IL-18, IL-27, IFN-γ, and TNF-α) and two anti-inflammatory cytokines (IL-1RA and IL-10) were elevated in COVID-19 patients compared to healthy controls." (PMID 39408907, 2024). "In patients with severe COVID-19, anti-SARS-CoV-2 antibodies and pro-inflammatory cytokines and chemokines (IL-6, CXCL-10, and HGF) were significantly elevated." (PMID 39063142, 2024). "The aim of the current study was to assess the prognostic value of bio-ADM and IL-6 regarding AKI and critical illness (admission to ICU and/or in-hospital death) in patients with COVID-19." (PMID 38336628, 2024). "As previously reported, IL-6 plays a critical role in triggering the cytokine storm observed in COVID-19 patients, and it may serve as a predictive marker for respiratory failure, aiding in the stratification of patients who could potentially benefit from early anti-IL-6 treatment." (PMID 38617587, 2024). "It has also been observed that elevated IL-6 levels disrupt the production and functionality of thyroid-stimulating hormone (TSH), paving the way for the pathogenesis of thyrotoxicosis in COVID-19." (PMID 39767735, 2024). "It was found that the severe COVID-19 cases showed stronger NF-κB activation, as well as higher levels of C-reactive protein (CRP), interleukin-6 (IL-6), ferritin and D-dimer." (PMID 37872376, 2024).